GCKR (glucokinase regulator)
Diseases named in the same sentence as GCKR in open-access papers (continued):
Sharing a sentence is not in itself a finding about the gene and the disease.
diabetes (42 papers, 2007 to 2025). "Glucokinase regulator (GCKR) is a regulatory protein that inactivates glucokinase in liver and pancreatic islet cells and has been previously associated with hyperlipidemia and diabetes." (PMID 41054850, 2025). "For instance, the GCKR (glucokinase regulatory protein) locus showed a strong association with ∆Age (p-value=8*10–12); however, the association disappeared when we excluded individuals diagnosed with diabetes." (PMID 40497443, 2025). "GCKR, influencing glucose metabolism, has variations associated with diabetes risk, while PPARG plays a pivotal role in adipogenesis and insulin sensitivity, highlighting its importance in T2DM37,38." (PMID 39020091, 2024). "The association between GCKR and TG further supports a biological mechanism between diabetes and TG." (PMID 33407432, 2021). "These variants correspond to several well-known target genes, such as the GCKR gene encoding a glucokinase regulatory protein that is known to be involved in the pathogenesis of diabetes mellitus." (PMID 32403311, 2020). "A meta-analysis has also shown that GCKR rs780094 T allele is a protective factor against diabetes and obesity." (PMID 31924263, 2020). "As further examples, the glucokinase regulator (GCKR) gene is a risk locus for several diabetes-relevant traits, and genetic variants at the carbamoyl-phosphatase 1 (CPS1) locus are associated with risk factors for chronic kidney disease." (PMID 23414815, 2013). "In the Diabetes Genetics Initiative genome-wide association study, the GCKR rs780094 A allele was found to be strongly associated with hypertriglyceridemia in populations from Finland and Sweden." (PMID 21569451, 2011). "As previously suggested, despite the advantages of modulating GCKR level in improving the regulation of glucose metabolism and reducing the risk of diabetes and kidney disease, its potential adverse side effects such as gout and dyslipidemia need to be taken into account." (PMID 39921581, 2025). "GCKR is a well-known gene associated with diabetes, and diabetes is a risk factor for AMD34." (PMID 37253714, 2023). "Most of the annotated SNPs have been implicated in multiple phenotypic traits, with the top pleiotropic SNP, rs1260326 in the GCKR gene being associated with 113 traits, from diabetes, glucose and glycemic pregnancy traits to anthropometric traits and various biomarkers." (PMID 36143166, 2022). "Also, an association between rs780094 polymorphism of GCKR and diabetes, particularly in Asian population has reported in a previous study." (PMID 31924263, 2020). "Further research is needed to determine whether specific GCKR haplotypes are associated with increased or decreased risk of diabetes in dogs." (PMID 26863414, 2016). "Additionally, while our sample sizes are limited, it is unlikely that GCKR CNV alone plays a role in diabetes risk in dogs." (PMID 26863414, 2016). "Interestingly, GCKR is a diabetes risk locus that inversely modulates triglyceride and fasting glucose levels." (PMID 23414815, 2013). "Thus, the combination of these two chemical shifts likely provides a combined measure of two main diabetes-risk readouts that have been independently associated with the GCKR locus before." (PMID 23414815, 2013). "Future efforts regarding GCKR target development should focus on other forms of diabetes (either genetic or T2DM in general) and related metabolic diseases such as metabolic dysfunction‐associated fatty liver disease." (PMID 39921581, 2025). "Two optimized molecules, AMG‐1694 and AMG‐3969, were advanced into preclinical models of diabetes and demonstrated efficacy in all tested diabetic models by reversing the inhibitory effect of GCKR on GCK activity and promoting GCK translocation." (PMID 39921581, 2025). "In their study, the genes GCKR, KCNJ11, and TCF7 were associated with hypertriglyceridemia and diabetes, while the LPIN1 and SLC22A1 genes were linked to a favorable response to antidiabetic drugs like rosiglitazone and metformin." (PMID 39408795, 2024).
diabetes (continued). "Critically, as an essential gene in the glucose metabolism pathway, the contribution of the GCKR gene to NASH/fibrosis is highly dependent on diabetes status." (PMID 37711901, 2023). "We examined the association between CDKAL1 rs10946398, GCK rs1799884, GCKR rs780094 and DGKB/TMEM195 rs2191349 gene polymorphisms and the development of post-transplant diabetes in kidney transplant patients treated with tacrolimus." (PMID 37628646, 2023). "Of any SNP on the 500 K array, an intronic GCKR SNP (rs780094) explained the greatest proportion of blood TG variance in the Diabetes Genetics Initiative study." (PMID 17903299, 2007). "They did not observe a significant association between either the GCKR SNP or progression to diabetes in the Diabetes Prevention Program." (PMID 38918799, 2024). "Using Metascape, we found that 4 genes (AZGP1, DLK1, GCKR and NEGR1) are linked to diabetes." (PMID 38184718, 2024). "The phenotypic manifestations of individual gene mutations could be amplified by interactions between genes and the environment, with the GCKR gene exhibiting strong synergistic effects alongside metabolic factors, especially insulin resistance and diabetes." (PMID 37711901, 2023). "Because of its role in regulating blood glucose homeostasis, it has previously been suggested that GCKR copy number may play a role in diabetes incidence in some dog breeds." (PMID 26863414, 2016). "The liver-specific Gckw/− mice show mild glucose elevation, thus diabetes might contribute to the cytoplasmic GCKR localization." (PMID 25849650, 2015). "Using a large, population-based cohort, our study replicated all previous associations of the GCKR rs780094 polymorphism with metabolic traits, including fasting glucose, insulin, post-OGTT glucose, CRP, and triglyceride concentrations and diabetes prevalence among white participants." (PMID 20661421, 2010). "Given that disease activity in susceptible individuals may fluctuate depending on environmental triggers, it may be crucial to further evaluate the impact of GCKR effect alleles on the histological progression of NAFLD in populations with impaired metabolism, particularly diabetes." (PMID 37711901, 2023). "Additionally, there was a nominal association between T allele at rs1229984 and diabetes and eGFR associated with T allele at rs12603262 (GCKR gene) that was non-significant on accounting for multiple tests." (PMID 35633389, 2022). "The mRNA expressions of GCK, GCKR, GLIS3 and CDKN2B, known to be related to diabetes mellitus, were examined by RT-PCR." (PMID 37049638, 2023). "RT-PCR analysis of blood RNA obtained from NS-3 treated people with T2DM for 24-weeks resulted down-regulation of gene expression in diabetes biomarkers (IRS-1, SOD-2, GCKR, IGFPB-2) compared to pre-dose values." (PMID 36540866, 2022). "First, as already shown by us for TCF7L2 and GCKR, a role of CACNA1E in determining beta cell function can be detected also in overt diabetes." (PMID 22427875, 2012). "In addition, isolated compounds 3, 4, 6 and 7 had an effect that significantly changed the mRNA expressions of GCK, GCKR, GLIS3 and CDKN2B, which are related to diabetes mellitus in the alloxan-induced zebrafish." (PMID 37049638, 2023). "The aim of this study was to evaluate the association of selected polymorphisms of genes affecting carbohydrate metabolism, such as CDKAL1 rs10946398, GCK rs1799884, GCKR rs780094 and DGKB/TMEM195 rs2191349, with the development of post-transplant diabetes in kidney transplant patients." (PMID 37628646, 2023). "The lack of evidence on the association of polymorphisms of other analysed genes involved in glycaemic regulation (GCK, GCKR, DGKB/AGMO) with the risk of post-transplant diabetes in kidney transplant recipients suggests that they do not play a key role in the development of this type of diabetes." (PMID 37628646, 2023).
diabetes (continued). "With the exception of the SNX17 signal near GCKR, there were notably few that were known blood pressure, diabetes or CAD signals, and of these, they were not the most strongly associated variants for these traits suggesting that the variants identified as associated with ACR are likely pleiotropic." (PMID 31630189, 2019).
metabolic syndrome (39 papers, 2010 to 2025). A cluster of metabolic risk factors for CARDIOVASCULAR DISEASES and TYPE 2 DIABETES MELLITUS. "In particular, the rs1260326 polymorphism in GCKR showed a 21% increase in susceptibly to metabolic syndrome." (PMID 38785970, 2024). "Weighted genetic risk scores from the combination of GCKR rs143881585 and rs146175795 revealed a significant association with metabolic syndrome." (PMID 35328045, 2022). "In this work, we compared predictive models for metabolic syndrome using the information on demographic and clinical and genetic data (functional variants of GCKR gene) on patients from TCGS." (PMID 35397593, 2022). "We analyzed our data to explore the association between the GCKR variants and metabolic syndrome components." (PMID 35365700, 2022). "NADH/NAD+ reductive stress in the liver emerges as the causal mechanism for features of the metabolic syndrome associated with hypomorphic GCKR, such as hepatic insulin resistance and increased triglyceride release." (PMID 34986329, 2022). "Like rs780094, rs780093 is also a common intronic variant in the GCKR gene that has been associated with polygenic dyslipidemia and high TG levels." (PMID 35397593, 2022). "We discovered that the combined low-frequency and rare variants rs143881585 and rs146175795 in the GCKR gene are highly linked with the risk of metabolic syndrome (p = 1.83 × 10−6) using WGRS from rs143881585 and rs146175795 variants." (PMID 35328045, 2022). "In this work, variants in the GCKR gene, as well as clinical and demographic measures, will be utilized to build predictive models for metabolic syndrome." (PMID 35397593, 2022). "We replicated associations of the common GCKR variants with metabolic syndrome components, including fasting blood sugar and triglyceride levels in Iranian adults." (PMID 33602293, 2021). "Elevated triglyceride levels had the strongest association with GCKR selected variants among the metabolic syndrome components." (PMID 33602293, 2021). "For example, several GWA studies have identified associations between GCKR and elevated plasma glucose, atherogenic dyslipidemia, and vascular inflammation." (PMID 22022282, 2011). "Analyzing the records of the patients, a positive association of prevalence the GCKR homozygous functional variants and carotid intima-media thickness was found in the metabolic syndrome patients." (PMID 21114848, 2010). "PheWAS found that targeting GCKR may improve renal function and glucose homeostasis but cause dyslipidemia and uric acid abnormalities." (PMID 39921581, 2025). "PheWAS further predicted that the intervention of GCKR can simultaneously prevent kidney disease but may be susceptible to side effects (e.g., dyslipidemia, gout), which need further research." (PMID 39921581, 2025). "A retrospective cohort study from Iranian adult subjects identified a strongly associated GCKR variant with the prevalence of metabolic syndrome, and genetic variants of GCKR have been demonstrated to be involved in hepatic redox and contribute causally to key metabolic traits and diseases." (PMID 36627697, 2023). "In addition to rs1260326, the low-frequency and rare GCKR variants rs143881585 and rs146175795 were linked to metabolic syndrome, but the p values (0.0402 and 0.0005, respectively) fell short of the statistical significance cut-off (1.0 × 10−5)." (PMID 35328045, 2022). "Previous studies reported that common functional variants (rs780093, rs780094, and rs1260326) in the glucokinase regulator gene (GCKR) were associated with metabolic syndrome despite the simultaneous association with the favorable and unfavorable metabolic syndrome components." (PMID 33602293, 2021). "Our results support that rs780094 and rs1260326 functional variants of the GCKR gene are inversely associated with serum triglycerides and fasting plasma glucose levels, as it was already reported for diabetic and metabolic syndrome patients in some other populations." (PMID 21114848, 2010).
metabolic syndrome (continued). "Furthermore, T alleles in GCKR‐rs780094 and GCKR‐rs1260326 are linked to IR and metabolic syndrome." (PMID 40202351, 2025). "Because four low-frequency and rare GCKR variants have a strong and persistent connection with serum triglyceride levels, aggregation of their effects may increase the risk of metabolic syndrome independently of the established risk of common polymorphism rs1260326." (PMID 35328045, 2022). "Our findings, by the combination of GCKR variants rs143881585 and rs1461755795, add to the growing body of evidence that GSKR plays a critical role in the development of metabolic syndrome." (PMID 35328045, 2022). "GCKR encodes glucokinase regulatory protein (GCKR), which exerts a significant role in developing the components of the metabolic syndrome, including triglyceride levels and glucose metabolism." (PMID 34986901, 2022). "In this study, we constructed GRSs composed 7 genetic variants (ANGPTL3 rs10889353, APOB rs7557067, GCKR rs780092, C2orf16 rs1919127, TRIB1 rs2954029, FADS1-FADS2-FADS3 rs174547, and APOA5 rs2266788) associated with dyslipidemia using GWAS studies." (PMID 33339179, 2020). "With regards to GCKR, our sensitivity analyses showed a highly significant association between the established GCKR variant and NAFLD only when dyslipidemia was included in the NAFLD definition." (PMID 32841307, 2020). "Three missense variants of metabolic syndrome-related genes, namely, rs671 in ALDH2, rs1169288 in HNF1A and rs1260326 in GCKR, significantly associate with AAT levels (P≤1.5 × 10−12)." (PMID 26174136, 2015). "Our data revealed that multiple low-frequency and rare GCKR exonic mutations are also significantly associated with serum triglyceride and albumin levels and metabolic syndrome, independent of rs1260326 genotypes." (PMID 35328045, 2022). "It has also been shown by others that the GCKR variant associates with dyslipidemia, while this is not the case for many other NAFLD risk-increasing genotypes such as PNPLA3 and that it increases the risk of NAFLD in obese individuals." (PMID 32841307, 2020). "GWAS and multiple candidate gene studies have identified GCKR variants as being linked to several metabolic parameters, including triglyceride (TG) levels, insulin resistance, and fasting plasma glucose levels, as well as metabolic disorders like T2DM and dyslipidemia." (PMID 38997780, 2024). "Apart from the influence of triglycerides, the GCKR variant, which was reported to be associated with decreased risk of T2DM but increased risk of dyslipidemia and fatty liver disease, may also play an important role to explain the pleiotropic pathways been identified." (PMID 37286992, 2023). "Similarly, the GCKR variant rs1260326 has been correlated with metabolic traits, such as higher levels of triglycerides and a higher incidence of dyslipidemia, without the onset of metabolic syndrome and T2DM." (PMID 37829557, 2023). "Moreover, multiple low-frequency and rare GCKR variants were found to contribute to various aspects of cardiometabolic traits, such as serum triglyceride and albumin levels and metabolic syndrome, in this Taiwanese population, independent of the rs1260326 variant." (PMID 35328045, 2022). "In the Women’s Genome Health Study, metabolic-syndrome related genes, such as LEPR, HNF1A, IL6R, and GCKR, were correlated to CRP expression and inflammation." (PMID 35845045, 2022). "For example, MUC1, SLC2A9, GCKR, and PKD2 may influence other metabolic syndrome–related traits such as blood pressure and FG." (PMID 31408958, 2019). "Initial evidence has been gathered on the interaction between GCKR variation and diet in the pathogenesis of dyslipidemia, although no data are yet available specifically for NAFLD." (PMID 28714900, 2017). "Importantly, both GCKR and IL6R were reported in metabolic syndrome." (PMID 38785970, 2024).